EGFR (epidermal growth factor receptor)
Diseases named in the same sentence as EGFR in open-access papers (continued):
Sharing a sentence is not in itself a finding about the gene and the disease.
endometrial cancer (continued). "First, knockdown of EGFR expression by siRNA or blockage of its tyrosin kinase activity using lapatinib (an EGFR inhibitor) inhibited phosphorylation of FAK induced by E2, G1 or OHT in RL95-2 endometrial cancer cells, suggesting that estrogen-induced GPR30 signaling is mediated through EGFR." (PMID 24039841, 2013). "In addition, knockdown of EGFR expression by siRNA also inhibited E2- and tamoxifen-induced phosphorylation of FAK in endometrial cancer cells." (PMID 24039841, 2013). "In summary, to the extent that Ishikawa H cells model type I tumors, it is predicted that type I but not type II endometrial cancers have the capacity to respond therapeutically to EGFR-targeted tyrosine kinase inhibitors." (PMID 20579378, 2010). "Both HER2-overexpressing endometrial cancer cell lines had significantly lower IC50 values compared with nonoverexpressing cell lines (mean IC50 value 0.33 vs 4.15; P=0.024), and EGFR expression was significantly inversely correlated with IC50 values (Spearman ρ, r=−0.57, P=0.011)." (PMID 18334972, 2008). "Aside, PR phosphorylation via the EGFR pathway leads to ubiquitination, which could explain why endometrial cancer cells preferentially lose PR and do not respond to progestin therapy." (PMID 35821038, 2022). "In the present study, RIP of EpCAM through EGF/EGFR signaling could neither be observed in an array of carcinoma cell lines nor be reproduced in RL95-2 endometrial carcinoma cells, independently of time points and EGF concentrations used." (PMID 30261040, 2018). "In addition, we confirm that endogenously expressed LRIG2 and EGFR proteins are associated in endometrial carcinoma cells, whereas LRIG2 does not regulate EGFR mRNA expression." (PMID 29358688, 2018). "Therefore, EGFR expression did not appear to impact disease progression in well-differentiated endometrioid endometrial cancer, but did seem to affect disease progression in undifferentiated nonendometrioid endometrial cancer." (PMID 19088718, 2009). "Expression of EGFR, its ligands, HER3, AR, and post-EMT markers warrant further evaluation to help define patients with HER2-nonoverexpressing endometrial cancer most likely to benefit from lapatinib." (PMID 18334972, 2008). "We first investigated the expression of EGFR family members EGFR, HER-2 and HER-4 by immunohistochemistry using 63 surgical specimens of endometrioid-type endometrial cancers, on the basis of the known finding that HER-3 expression is not upregulated in endometrial cancer." (PMID 20664599, 2010).
chronic myeloid leukemia (129 papers, 2007 to 2025). "Some examples of target genetic mutations include EGFR in lung cancer, which responds to gefitinib and erlotinib therapy, and the Bcr-Abl fusion gene in chronic myelogenous leukemia, which is effectively treated with imatinib." (PMID 41155542, 2025). "Small molecule targeted therapies, e.g. tyrosine kinase inhibitors (TKIs), are mainly used as single agents in treating monogenic cancer disease such as chronic myeloid leukemia, EGFR-mutated NSCLC, or advanced renal cancers." (PMID 33142728, 2020). "Inhibition of deregulated kinase activities by small molecule inhibitors has been proven to be an effective treatment for many types of diseases, including chronic myeloid leukemia, epidermal growth factor receptor (EGFR)-mutated, and ALK-rearranged NSCLC." (PMID 28245558, 2017). "For instance, BCR-ABL kinase inhibitors are used for chronic myeloid leukemia and EGFR tyrosine kinase inhibitors are used for NSCLC with EGFR mutations." (PMID 38992694, 2024). "Cells of chronic myelogenous leukemia (CML) release AREG that targets EGFR on MSCs and alters gene expression." (PMID 37563650, 2023). "Comparable thresholds of >2.31 and >2.5 were used in studies on TERC gene amplification in chronic myeloid leukemia and EGFR copy number in metastatic lung cancer." (PMID 28415661, 2017). "Another attribute of some well-known oncogenes, such as BCR-ABL fusion in chronic myeloid leukemia or mutant EGFR or KRAS in LUAD, is the dependence on sustained expression of those oncogenes for the maintenance of cell growth or viability." (PMID 27776121, 2016). "In conclusion, we showed that chronic myelogenous leukaemia cell‐derived exosomes modulate bone marrow microenvironment through activation of EGFR in stromal cells." (PMID 27196940, 2016). "The use of EGFR inhibitors in lung cancer and Imatinib in chronic myeloid leukemia (CML) patients are two relevant examples." (PMID 26327537, 2015). "Molecular targeting therapy using TKIs is currently one of the most successful forms of treatment in the clinic, and includes imatinib targeting BCR-ABL in chronic myeloid leukemia (CML) and gefitinib/erlotinib in EGFR-mutated LAD." (PMID 24928511, 2014). "Results indicate the relationship of the drug with terms associated to protein serine/threonine kinases and protein kinase B. In chronic myeloid leukemia studies, altered expression levels of key signaling molecules in the EGFR/MAPK pathway were observed in PD153035-treated mouse groups." (PMID 37633093, 2023). "In addition to exosomal microRNAs, chronic-myelogenous-leukemia-derived exosomal amphiregulin (AREG) activated Epidermal growth factor receptor (EGFR) and SNAIL expression." (PMID 32252322, 2020). "For example, blockade of signaling molecules within the Ras/MEK or PI3K/mTOR pathways might augment the effects of EGFR therapeutics, similar to their effects on chronic myelogenous leukemia cells when used in conjunction with the BCR-ABL inhibitor imatinib." (PMID 17973573, 2007). "It is interesting to draw analogies between TKIs targeting EGFR and TKIs specific to BCR-ABL1, a fusion tyrosine kinase that acts as the driver of chronic myeloid leukemia (CML)." (PMID 37894376, 2023). "In 2012, Ng reported that BIM deletion polymorphism mediated primary resistance to TKIs in cancers including chronic myeloid leukemia (CML) and EGFR‐mutant NSCLC; this; was confirmed by in vitro cell culture experiments and clinical data." (PMID 32508032, 2020). "CRKL, best known as a substrate of BCR-ABL kinase in chronic myelogenous leukemia (CML) with Philadelphia chromosome, has been described as an oncogene that is amplified in a subset of EGFR-inhibitor resistant NSCLCs." (PMID 27078848, 2016). "Recently a germline mutation in the proapoptotic gene BIM was associated with the resistance to tyrosine kinase inhibitors in chronic myeloid leukemia (CML) and epidermal growth factor receptor (EGFR) mutant NSCLC." (PMID 24782887, 2014).
chronic myeloid leukemia (continued). "The chronic myeloid leukemia K562 cell line, neither expressing EGFR nor ABCG2, was transduced with vectors containing the ABCG2 wt, the SNPs: 34 G > A and 421 C > A, or with empty vector (K562/ve)." (PMID 32266784, 2020). "In addition, in chronic myeloid leukemia model, we have previously shown that AREG is involved in the activation of EGFR downstream signaling in mesenchymal stromal cells leading to the expression and release of IL8." (PMID 30621731, 2019). "In dynamic PET scans of rats bearing two xenografts, a gradual accumulation of the tracer in A431 (EGFR-positive), but not in human chronic myeloid leukemia K562 (EGFR-negative) tumors, was observed." (PMID 18991714, 2008). "Additionally, ethanol-extracted G. lucidum has been shown to enhance cellular autophagy mechanisms for protection while simultaneously suppressing the expression of epidermal growth factor receptor (EGFR) and the PI3K/AKT/mTOR signaling pathway in chronic myelogenous leukemia-affected cells." (PMID 40417000, 2025).
colorectal tumors (126 papers, 2007 to 2026). "Targeting epidermal growth factor receptor (EGFR) counteracts inhibition of natural killer cell function by colorectal tumor-associated fibroblasts." (PMID 39100676, 2024). "Our study also establishes the therapeutic potential of the concurrent blockade of KRASG12D and EGFR as an improved treatment for patients with KRASG12D-mutated colorectal tumors." (PMID 37020035, 2023). "In cetuximab-resistant colorectal tumors, the following somatic mutations are observed that map to the cetuximab epitope on EGFR: G441/465R, G441/465E, and K443/467T." (PMID 33670650, 2021). "Earlier testing has the potential to identify resistance conferring mutations and direct patients away from a futile therapy such as EGFR directed therapy for KRAS mutations in colorectal tumors." (PMID 32760731, 2020). "All 4 treatments produced meaningful responses, with particularly notable objective response rates in patients with human EGFR-2–amplified/overexpressing colorectal tumors (38%) and BRAF V600-mutated NSCLC (43%)." (PMID 29765547, 2018). "It has been shown in several experiments that the KRAS mutations in primary colorectal tumors play a prognostic role as a predictor of resistance to the anti-EGFR antibodies." (PMID 28580315, 2017). "Advances in the understanding of colorectal tumor biology and oncogenic signaling have enabled the development of biomarker-guided therapies targeting alterations in EGFR, BRAFV600E, KRAS mutations and HER2 amplifications, improving outcomes in selected patient populations." (PMID 42074578, 2026). "In this situation, it is clear that the only evaluation of KRAS mutation status in primary colorectal tumor may be inadequate to predict response to anti-EGFR therapy of the corresponding CRLM and may provide limited information prior to multimodal treatment." (PMID 33946899, 2021). "For example, it has been shown that colorectal tumors that are wild type for KRAS are often sensitive to targeted epidermal growth factor receptor (EGFR) blockade; however, KRAS mutations become detectable at the time of acquired resistance to this targeted drug." (PMID 26912072, 2016). "We reasoned that these findings might be mechanistically explained if cells carrying RAS mutations were latently present in colorectal tumours before exposition to EGFR blockade." (PMID 27929064, 2016). "Preclinical studies showed it inhibited colorectal tumour cell growth and reduced EGFR, pEGFR, pMAPK, and pAKT levels." (PMID 40940907, 2025). "EGFR-XPAT protein showed potent in vivo antitumor activity in huPBMC-engrafted mice bearing HT-29 (BRAFmut) human colorectal tumors." (PMID 36997747, 2023). "Other than RAS genes that predict anti-EGFR sensitivity, PIK3CA mutations have prognostic implication in colorectal tumors." (PMID 37483495, 2023). "These are platinum-based therapies (across tumors originating in the colorectum or the lung), taxanes (across breast and prostate tumors), anti-EGFR drugs (across lung tumors) and pyrimidine analogs (across colorectal tumors)." (PMID 36780550, 2023). "PAR2 also modulates transactivation of other cell surface receptors (i.e., EGFR) that are frequent drivers of colorectal tumor progression." (PMID 35883559, 2022). "To date, liquid biopsies have shown the selective pressure of anti-EGFR therapies in patients with RAS-wild-type * colorectal tumors, in that acquired resistance to EGFR blockade is often driven by the emergence of KRAS/NRAS mutations in plasma." (PMID 35159069, 2022). "EGFR is upregulated in several tumor types, including lung and colorectal tumors making EGFR an exquisite therapeutic target." (PMID 35409325, 2022). "Healthy colon cells express EGFR as well, albeit at lower levels compared to most colorectal tumors." (PMID 35035479, 2022).
colorectal tumors (continued). "As expected from human CRC studies, increased Egfr mRNA expression and EGFR protein levels were detected in colorectal tumors from AOM/DSS-treated mice in comparison to normal tissue." (PMID 34830971, 2021). "CTSD is highly expressed in colorectal tumors and positively correlated with the expression of EGFR." (PMID 32331211, 2020). "The KRAS oncogene produces colorectal tumors resistant to anti-EGFR therapies by activating the Ras-Raf-MAPK pathway downstream of EGFR." (PMID 32054005, 2020). "KRAS mutations in colorectal tumour (CRC) progression are associated with acquired resistance and reduced response to anti-epidermal growth factor receptor (EGFR) therapies." (PMID 33144898, 2020). "Genomic studies performed through liquid biopsies widely elucidated the evolutionary trajectory of RAS mutant clones under the selective pressure of EGFR inhibitors in patients with wild type RAS primary colorectal tumors." (PMID 30621206, 2019). "Between 60 and 80% of colorectal tumors overexpress the EGFR; although this characteristic was historically thought to be predictive of response to cetuximab and panitumumab, in more recent years this notion has not held up in practice." (PMID 31616627, 2019). "We have reported previously the growth response of human colorectal tumour cell lines to treatment with anti-EGFR mAb ICR62 and cytotoxic drugs." (PMID 30899442, 2019). "EGFR was positive in 92% of 619 tumor samples in a large series of colorectal tumors and EGFR expression correlated with favorable survival." (PMID 29850390, 2018). "Clinicopathological analysis showed that the overexpression of RPN2 and EGFR was positively correlated with colorectal tumor size." (PMID 29069815, 2017). "Recently, the epidermal growth factor receptor (EGFR) has become a promising target for it is activated in colorectal tumors." (PMID 28167959, 2017). "The differential impact of RAS and EGFR ECD mutations on PFS and the dynamics observed in liquid biopsies suggest that colorectal tumours evolve along distinct molecular trajectories according to the occurrence of specific resistance mutations." (PMID 27929064, 2016). "This was derived from an individual carrying a quadruple wild-type (KRAS, NRAS, BRAF and PIK3CA) colorectal tumour, and thus recapitulates the molecular profile of patients sensitive to anti-EGFR antibodies." (PMID 26392303, 2015). "By using a phosphokinase arrays with human colorectal tumors we identified activated kinases, including the Epidermal Growth Factor Receptor (EGFR), components of the PI3K/mTOR pathway (AKT and S6), and STAT, among others." (PMID 26418718, 2015). "The same experimental strategy was then applied to an independent PDX that was also derived from a quadruple wild-type (KRAS, NRAS, BRAF and PIK3CA) colorectal tumour and was sensitive to EGFR blockade." (PMID 26392303, 2015). "Three different macroscopic subtypes of colorectal neoplasms display distinct carcinogenetic pathways in EGFR networking." (PMID 25551625, 2014). "This cascade is activated by the EGFR that is overespressed in 50-80% of colorectal tumors and therefore represent a suitable target for the anticancer therapies with monoclonal antibodies as cetuximab and paninutumab." (PMID 25267307, 2014). "In this study, we aimed to assess the frequency and distribution of EGFR pathway alterations in three subtypes of colorectal neoplasms." (PMID 25551625, 2014). "For example, colorectal tumors overexpressing epidermal growth factor receptor (EGFR) respond to anti-EGFR antibody treatment only in the absence of mutations that constitutively activate KRAS." (PMID 24337485, 2014). "Within this context, the KRAS gene bears significant predictive value relative to the use of anti-EGFR therapies in colorectal neoplasms." (PMID 29147353, 2013). "It is thus possible that COX-2 and EGFR signalling pathways are inversely related to each other in most colorectal tumors." (PMID 24171795, 2013).
colorectal tumors (continued). "Higher expression of the epidermal growth factor receptor (EGFR) has been found in colorectal tumors of more advanced stage and poor differentiation, and those exhibiting vascular and lymphatic invasion." (PMID 24276379, 2013). "We have previously reported the correlation of VEGF, EGFR, and 5-FU metabolism-related genes between primary colorectal tumor and liver metastases." (PMID 22409860, 2012). "For instance, overexpression of the epidermal growthfactor receptor (EGFR) is observed in three-fourths of primary colorectal tumors and provides support fortargeting these cells using panitumumab, a monoclonal antibody against EGFR." (PMID 23336100, 2012). "In fact although we are now able to exclude from anti-EGFR treatment patients with putative refractory colorectal tumours (i.e. those harboring a K-RAS mutant status), we are still unable to select responding patients among those without K-RAS mutations." (PMID 22490361, 2012). "For study purposes when results for EGFR methylation status in primary colorectal tumours and corresponding metastases resulted conflicting, only the methylation status in metastases was considered biologically relevant." (PMID 21559018, 2011). "EGFR GCN ≥ 2.12 was present in 28 (64%) colorectal tumors, whereas it was < 2.12 in the remaining 16 (36%) patients." (PMID 19712476, 2009). "K-RAS wild type colorectal tumors show an improved response rate to anti-EGFR monoclonal antibodies." (PMID 19712476, 2009). "FISH EGFR GCN ≥ 2.6 was present in 15 (40%) colorectal tumors, whereas it was < 2.6 in the remaining 22 (60%) patients." (PMID 19712476, 2009). "In order to investigate the relation between colorectal tumour grades and Id-1, EGFR and VEGF, the tumours were divided into three groups: grade I (G I) (n = 10), grade II (G II) (n = 21) and grade III (G III) (n = 15) tumours." (PMID 19014499, 2008). "Experimental evidence indicates that polyphenols in healthy plant foods, such as ferulic acid and p‐coumaric acid in whole grains, hydroxytyrosol in olive oil59 and epigallocatechin‐3‐gallate in green tea, can inhibit colorectal tumour cell growth via downregulation of EGFR expression." (PMID 35998061, 2022). "However, blockade of EGFR by the tyrosine kinase inhibitor gefitinib in mice displaying established colorectal tumors seemed to decrease polyp sizes, pointing to opposing roles of EGFR signaling in the resolution of intestinal inflammation and tumor growth." (PMID 34830971, 2021). "EGFR overexpression was detected in 80–90% of colorectal tumours." (PMID 30858756, 2019). "Moreover, the treatment of patients with mutant KRAS colorectal tumors with EGFR inhibitors seemed to aggravate disease progression." (PMID 30858928, 2019). "Besides, AC regulation on the anti-apoptotic pathway was reported to include PI3K/Akt and activator of transcription (STAT), through the over-expressed EGFR in colorectal tumors." (PMID 31349708, 2019). "MAPK signaling downstream of EGFR controls colorectal tumor cell proliferation." (PMID 29108242, 2017). "The trial is designed to include an enriched population of patients with KRAS and NRAS wild-type rectal cancer due to evidence of lack of benefit from anti-EGFR strategies in KRAS or NRAS mutated colorectal tumors." (PMID 27655166, 2016). "Despite the clarified mechanism of the lack of response of colorectal tumors with mutated RAS gene to the EGFR-directed therapy, certain tumors having wild-type RAS gene are known not to respond to that therapy." (PMID 27127793, 2016). "Furthermore, EGF receptor (EGFR)-dependent colorectal tumor xenografts in nude mouse exerted anti-proliferative and growth suppression effects by injecting secineH3." (PMID 24618737, 2014). "In addition, increased EGFR expression in BRAF(V600E) colorectal tumors has been shown to correlate with vemurafenib resistance." (PMID 24023633, 2013). "Therefore, our aim was to analyze relationships between COX and EGFR in peroperative colorectal tumor biopsies." (PMID 24171795, 2013).